TK1 (thymidine kinase 1)
Diseases named in the same sentence as TK1 in open-access papers (continued):
Sharing a sentence is not in itself a finding about the gene and the disease.
thyroid cancer (8 papers, 2019 to 2025). "In this study, we identified TK1 as a potential tumor associated antigen and constructed the immune landscapes of thyroid cancer." (PMID 39403328, 2024). "The present study aimed to determine the role TK1 in the progression of thyroid cancer and to explore the underlying molecular mechanisms." (PMID 32064235, 2019). "In addition, TK1 silencing in thyroid carcinoma cell lines caused a decrease in cell proliferation, invasion, and migration and induced apoptosis." (PMID 35203388, 2022). "Moreover, the upregulated TK1 in the thyroid carcinoma cells was associated with the downregulation of miR-34a-5p." (PMID 32064235, 2019). "Disruption of TK1 suppresses the growth, invasion, and migration of thyroid cancer cells, as well as the induction of EMT." (PMID 39803822, 2025). "To validate, the TK1 expression levels in thyroid cancer were detected by immunohistochemistry and RT-qPCR." (PMID 39403328, 2024). "In the thyroid cancer, high levels of TK1 were correlated with the advanced clinical stage of patients with thyroid carcinoma." (PMID 32064235, 2019). "The in vitro functional studies showed that TK1 silencing suppressed thyroid cancer cell proliferation, invasion, migration, epithelial–mesenchymal transition (EMT) and induced cell apoptosis." (PMID 32064235, 2019). "Further studies showed that miR-34a-5p repressed TK1 expression in thyroid carcinoma cells via targeting the 3′UTR of TK1." (PMID 32064235, 2019). "The downregulated miR-34a-5p in thyroid carcinoma resulted in higher TK1 level, which promoted thyroid carcinoma cell proliferation, invasion, and migration." (PMID 32064235, 2019). "In summary, the results in this study demonstrated the upregulation of TK1 in thyroid nodules as well as thyroid carcinoma tissues." (PMID 32064235, 2019). "Silencing of TK1 suppressed cell proliferation, invasion, migration, and epithelial–mesenchymal transition, and also induced cell apoptosis in the thyroid carcinoma cell lines." (PMID 32064235, 2019). "In summary, first, these results demonstrated the upregulation of TK1 in thyroid nodules and thyroid carcinoma tissues; second, TK1 promoted thyroid carcinoma cell proliferation, invasion, and migration; lastly, TK1 was negatively regulated by miR-34a-5p." (PMID 32064235, 2019). "Further online data mining showed that TK1 expression was upregulated in thyroid carcinoma tissues, and higher expression of TK1 was correlated with shorter DFS of patients with thyroid carcinoma." (PMID 32064235, 2019). "In this study, it was showed that serum TK1 levels were upregulated in patients with thyroid nodules, suggesting that TK1 might be involved in the development of thyroid cancer." (PMID 32064235, 2019). "In vivo data showed that TK1 knockdown inhibited in vivo tumor growth of thyroid carcinoma cells." (PMID 32064235, 2019). "Taken together, the results in this study might imply that TK1 promoted thyroid carcinoma progression via P21 or growth and differentiation factor 15 by increasing cell proliferation, invasion, and migration." (PMID 32064235, 2019). "Furthermore, miR-34a-5p targeted the 3′ untranslated region of TK1 and suppressed the expression of TK1 in thyroid carcinoma cell lines." (PMID 32064235, 2019). "This study may provide novel insights into the role TK1 played in regulating thyroid carcinoma progression." (PMID 32064235, 2019). "Further online data mining showed that TK1 expression was upregulated in thyroid carcinoma tissues, and higher expression of TK1 was correlated with shorter disease-free survival of patients with thyroid carcinoma." (PMID 32064235, 2019). "Our study may provide novel insights into the role of TK1 in regulating thyroid carcinoma progression." (PMID 32064235, 2019). "The elevated expression of TK1 has been implicated in the progression of thyroid carcinoma, while the role of TK1 in thyroid carcinoma progression has not been explored." (PMID 32064235, 2019).
thyroid cancer (continued). "Animal studies showed that TK1 knockdown inhibited in vivo tumor growth of thyroid carcinoma cells." (PMID 32064235, 2019). "Collectively, the upregulation of TK1 may be related to downregulated miR-34a-5p expression, which contributed to the enhanced progression of thyroid carcinoma." (PMID 32064235, 2019). "In addition, the upregulated TK1 in thyroid cancer patient may be resulted from the downregulated miR-34a-5p, but the upstream and downstream molecular mechanisms were still unclear." (PMID 32064235, 2019). "Furthermore, the upregulation of TK1 in the thyroid cancer may be related to the downregulation the tumor-suppressive miR-34a-5p." (PMID 32064235, 2019). "Besides, the in vitro studies showed the consistent upregulation of TK1 in thyroid carcinoma cells." (PMID 32064235, 2019). "Silencing of TK1 suppressed cell proliferation, invasion, migration, and EMT and also induced cell apoptosis in the thyroid carcinoma cell lines." (PMID 32064235, 2019). "The elevated expression of thymidine kinase 1 (TK1) has been implicated in the progression of thyroid carcinoma, while the role of TK1 in thyroid carcinoma progression has not been explored." (PMID 32064235, 2019). "Unfortunately, the molecular mechanisms of TK1 in regulating thyroid carcinoma progression have not been explored yet." (PMID 32064235, 2019).
colon carcinoma (6 papers, 2018 to 2024). "Suzuki and colleagues reported that PD1 blockade increased the G2/M population in murine colon carcinoma cells, which have high TK1 activity." (PMID 38811918, 2024). "We found that the antibodies developed were able to detect membrane TK1 expression in lung, breast, prostate and colon cancer cells." (PMID 32317865, 2020). "We found a significant increase in the cytolysis of lung, breast and colon cancer cells by MNC when the anti-TK1 antibodies were added in comparison to controls." (PMID 32317865, 2020). "In this study, we present data supporting the expression and localization of TK1 on the cellular membrane of lung, breast, and colon cancer, suggesting TK1 as a surface marker for these malignancies and a different function for TK1 never reported before." (PMID 30214377, 2018). "In fact, A549 and NCI-H460 cells lines show higher expression of TK1 on the surface to breast and colon cancer cell lines reported in the literature." (PMID 30214377, 2018). "To conclude, in this study, we have demonstrated for the first time that FOXM1 has a crucial role in 5-FU drug resistance in colon cancer cells, through regulating some of the main 5-FU targets, including TYMS, TK-1 and TYMP." (PMID 30728402, 2019). "Analogously, in colon cancer a lack of increased TK1 activity during chemotherapy was related to a poor prognosis." (PMID 32423477, 2020).
ovarian carcinoma (6 papers, 2020 to 2025). A malignant neoplasm originating from the surface ovarian epithelium. "Materials and methods: The aim of this study was to investigate the role of thymidine kinase 1 (TK1) in combination with CA 125 or HE4 to serve as a potential diagnostic biomarkers for ovarian cancer." (PMID 36900385, 2023). "As a marker of cell proliferation, TK1 has been extensively studied in various cancers, including lung, breast, colorectal, esophageal, and ovarian carcinomas." (PMID 40564887, 2025). "In this study, we analyzed the diagnostic role of TK1 protein, TK1 activity, CA 125, HE4 as well as the ROMA index for the early detection of ovarian cancer in pre-menopausal and post-menopausal women in comparison with a group of matched controls." (PMID 36900385, 2023). "Here, an example photo shows TK1 IHC staining of hTK1-Ig-rmAb#5 in normal tonsil tissue, ovarian cancer tissue, and normal ovarian tissue." (PMID 36969497, 2023). "Only high expression of UBE2C, TK1, TACC3 and CXCR4 and low expression of MAOB were proved to be associated with poor prognosis of patients with ovarian cancer, suggesting the five genes were considered to be the key genes in ovarian cancer." (PMID 33123295, 2020). "Therefore, the TK1 protein is a promising serum biomarker that can complement CA 125 or HE4 in the diagnostics of the early stages of ovarian cancer." (PMID 36900385, 2023). "Enzymes involved in the salvage pathway, such as uridine-cytidine kinase (UCK) and thymidine kinase 1 (TK1), have also been found to be upregulated in ovarian cancer." (PMID 37233659, 2023).
pancreatic cancer (6 papers, 2019 to 2026). "Consistent with previous studies, TK1 has been shown to promote cell proliferation, migration, and invasion across various cancers, including liver and pancreatic cancer." (PMID 41584726, 2026). "A previous study discovered that TK1 promoted pancreatic cancer cell proliferative activity via the E2F1-TK1-P21 axis, which focused on cell cycle regualtion." (PMID 35311151, 2022). "The positive correlation between TYMP and TK1 expression in pancreatic tumours supports this possibility." (PMID 34132895, 2021). "It was reported in pancreatic cancer the silencing of TK1 suppressed cancer cell proliferation via inducing S phase arrest by P21 upregulation." (PMID 32064235, 2019). "Interestingly, the rate-limiting enzyme of FLT metabolism, the pyrimidine-metabolizing enzyme thymidine kinase-1 (TK-1), is overexpressed in pancreatic cancer cell lines and pancreatic cancer." (PMID 36555470, 2022). "Expression of these genes, which are involved in 5-FU conversion to FdUMP, also correlated with expression of the FdUMP efflux transporter ABCC5 (TK1 and ABCC5 r = 0.78, p = 0.001 and TYMP and ABCC5 r = 0.86, p < 0.0001) in pancreatic tumour." (PMID 34132895, 2021).
glioma (5 papers, 2021 to 2023). A benign or malignant brain and spinal cord tumor that arises from glial cells (astrocytes, oligodendrocytes, ependymal cells). "The ROC curves indicated a high diagnostic value of TK1 expression in patients of glioma; the areas under the ROC curve (AUC) were 0.682, 0.735, and 0.758 for 1 year, 3 years, and 5 years of glioma survival, respectively." (PMID 36831773, 2023). "Single-cell function analysis showed that TK1 was positively associated with proliferation, the cell cycle, DNA repair, DNA damage, and epithelial–mesenchymal transition in glioma." (PMID 36831773, 2023). "Time-dependent ROC curves indicated that TK1 expression had a high diagnostic value of TK1 expression in glioma patients, with an area under the curve (AUC) of 0.682, 0.735, 0.758 for 1-year, 3-year, and 5-year survival, respectively." (PMID 36831773, 2023). "Three types of TK1 alterations—missense mutations, splice mutations, and amplifications—were identified in 25 of 2706 glioma samples." (PMID 36831773, 2023). "Additionally, we found that missense mutations, splice mutations, and amplifications were involved in glioma samples, and our survival analysis showed that the TK1-altered group had better OS than the group with these alterations." (PMID 36831773, 2023). "Immunoinfiltration analysis indicated that TK1 expression might play different roles in low-grade glioma and glioblastoma multiforme tumor microenvironments, but TK1 expression was positively associated with activated CD4 and Th2, regardless of tumor grade." (PMID 36831773, 2023). "Therefore, future studies are warranted to clarify the diagnostic role of TK1 expression in cerebrospinal fluid samples for the early detection of gliomas." (PMID 36831773, 2023). "TK1 is expressed at high levels in gliomas, and the general survival is worse in patients with high TK1 expression." (PMID 37767092, 2023). "Next, we assessed the mRNA expression levels of TK1 in different grades of gliomas in four datasets and found that TK1 expression increased with the increasing glioma grade." (PMID 36831773, 2023). "Here, we first comprehensively explored TK1 profiles of expression, prognosis, functional signaling, and immune infiltration in glioma." (PMID 36831773, 2023). "In summary, our findings identified TK1 as a novel marker for predicting clinical outcomes and a potential target for glioma." (PMID 36831773, 2023). "Single-cell functional analysis revealed that TK1 expression positively correlated with the proliferation, cell cycle, DNA repair, DNA damage, and epithelial-mesenchymal transition of glioma cells." (PMID 37767092, 2023). "In this study, we conducted a series of bioinformatics analyses using the public multi-omics datasets to assess the relationships of the expression level of TK1 with glioma prognosis and clinicopathological variables." (PMID 36831773, 2023). "To begin, the transcriptional levels of TK1 expression between glioma and normal tissues were assessed via GEPIA2 databases." (PMID 36831773, 2023). "In conclusion, the current study comprehensively explored the malignant properties of TK1 in glioma through multiple levels of bioinformatics analysis." (PMID 36831773, 2023). "Together, these findings indicated that TK1 expression with other clinical factors performs well in predicting the prognosis of glioma." (PMID 36831773, 2023). "Using CancerSEA, we identified two GEO datasets (GSE57872 and GSE 102130) for assessing the functional characteristics of TK1 at a single-cancer-cell level in glioma." (PMID 36831773, 2023). "There is much research on the role of TK1 as a diagnostic biomarker for several cancer types including chronic lymphocytic leukemia (CLL), glioma, and others." (PMID 37767092, 2023). "The Kaplan–Meier curve, a predictive nomogram mode, and the time-dependent receiver operating characteristic (ROC) curve were established to assess the role of TK1 expression in glioma prognosis." (PMID 36831773, 2023).
glioma (continued). "TK1 was overexpressed in glioma compared with normal samples, and patients with elevated expression of TK1 had poor overall survival." (PMID 36831773, 2023). "We identified eight datasets and then used Kaplan–Meier survival curves to assess the prognostic role of TK1 in glioma." (PMID 36831773, 2023). "For this purpose we measured at early time after treatment the uptake of [18F]FLT and [18F]VC701 radiopharmaceuticals targeting thymidine kinase 1 (TK1) and Translocator Protein 18 kDa (TSPO) which are receptors associated with glioma malignancy." (PMID 34012924, 2021). "According to our predefined criteria, we identified that hsa-miR-1182, hsa-miR-129-5p, hsa-miR-132-3p, hsa-miR-139-3p, and hsa-miR-150-5p miRNAs may regulate TK1 expression in glioma by using the microRNA_198 and mRNA-array_301 datasets from the CGGA." (PMID 36831773, 2023). "Genetic alterations of TK1 in glioma were explored with cBioPortal." (PMID 36831773, 2023). "In addition, we assessed the biological role of TK1 in glioma development to illustrate its therapeutic value in glioma treatment." (PMID 36831773, 2023). "TK1 was overexpressed in TCGA glioma samples compared with GTEx normal profiles." (PMID 36831773, 2023). "However, the precise role of TK1 and its molecular mechanisms underlying glioma progression have not been fully explored." (PMID 36831773, 2023). "Moreover, we also found that TK1 was overexpressed in glioma cells compared with the SVG cell line." (PMID 36831773, 2023). "Together, these findings suggest that TK1 might act as an oncogene in glioma." (PMID 36831773, 2023). "Collectively, these miRNAs may regulate TK1 expression in glioma." (PMID 36831773, 2023). "Finally, we evaluated TK1 expression according to the pathological glioma subtype." (PMID 36831773, 2023). "Collectively, these findings suggested that TK1 might serve as a prognostic biomarker for glioma." (PMID 36831773, 2023). "For the first time, we revealed that a negative association between TK1 methylation and TK1 mRNA expression in glioma and methylation levels could determine OS in patients with glioma." (PMID 36831773, 2023). "Collectively, our findings indicated that these miRNAs might regulate TK1 expression in glioma." (PMID 36831773, 2023). "Therefore, we speculated that TK1 may also be involved in malignant biological behavior in glioma." (PMID 36831773, 2023). "PET imaging of herpes simplex virus thymidine kinase 1 (HSV1-TK+) CAR-T cells co-expressing the CAR and the reporter gene of HSV1-TK within the same cell has been tested in patients with glioma." (PMID 33632155, 2021). "First, we did not fully clarify the role of TK1 expression in the different pathological subtypes of gliomas because few datasets provided data on pathological subtypes, and various pathological subtypes were defined in the included datasets." (PMID 36831773, 2023). "In our analysis of transcriptional data collected from TCGA, GTEx, and GEO, we discovered that TK1 expression was higher in glioma tissue samples and cell lines than in normal samples or normal cell lines." (PMID 36831773, 2023). "However, the role of TK1 expression and its biological function in glioma had not been elucidated." (PMID 36831773, 2023).
non-small cell lung carcinoma (5 papers, 2012 to 2021). A group of at least three distinct histological types of lung cancer, including non-small cell squamous cell carcinoma, adenocarcinoma, and large cell carcinoma. "We investigate if thymidine kinase 1 in serum (STK1p) is a reliable prognostic marker for survival in non-small-cell lung carcinoma." (PMID 33552542, 2020). "A prospective investigation of serum thymidine kinase 1 concentration (STK1p) was performed to evaluate its prognostic value in patients with non-small-cell lung carcinoma (NSCLCs)." (PMID 33552542, 2020). "Moreover, these CAR cells specifically induce cell death and form clusters around the TK1-positive non-small cell lung carcinoma NCI-H460 cell line." (PMID 34476174, 2021).
acute lymphoblastic leukemia (4 papers, 2014 to 2024). Leukemia with an acute onset, characterized by the presence of lymphoblasts in the bone marrow and the peripheral blood. "Our results also correlated with some of our previous findings, which show that TK1 localizes on the surface of hematological malignancies such as Burkitt’s lymphoma, acute lymphoblastic leukemia, promyelocytic leukemia, and T-cell lymphoma cells." (PMID 30214377, 2018). "In one study it was shown that monomeric and dimeric forms of TK1 can be detected on the cell membrane of mononuclear cells (MNC) from patients with acute lymphoblastic leukemia (ALL) and acute myeloid leukemia (AML)." (PMID 32317865, 2020).
squamous cell carcinoma (4 papers, 2018 to 2024). A carcinoma arising from squamous epithelial cells. "Lung tissue array shows ~ 50% of the tissues stain positive for TK1 in both adenocarcinoma and squamous cell carcinoma." (PMID 30214377, 2018). "In addition, TK1 combined with CEA, CYFRA21-1, or NSE could improve the diagnosis of squamous cell carcinoma, adenocarcinoma, or small cell lung cancer, respectively." (PMID 33488842, 2020).
B-cell lymphoma (3 papers, 2021 to 2025). "The ROC curve analysis with the canine TK1 ELISA showed a significantly higher AUC compared to the dThd phosphorylation assay in the differentiation of T-cell lymphoma from B-cell lymphomas (p = 0.028)." (PMID 37808109, 2023). "The median value of TK1 protein in T-cell lymphoma was 0.23 ng/mL, while the median value in B-cell lymphoma was 1.8 ng/mL." (PMID 37808109, 2023). "Overall, the data indicate that cancer patients, especially those with B-cell lymphoma and certain solid tumors, have elevated TK1 and CRP levels compared to healthy controls, highlighting differences in inflammatory and tumor marker levels across these groups." (PMID 40351765, 2025). "However, in another study, dogs diagnosed with B‐cell lymphoma did have higher TK1 activity than those with T‐cell lymphoma." (PMID 34359096, 2021). "The highest concentration was found in B-cell lymphoma (mean: 2,874 pg/mL) whereas the MMT showed a much lower mean TK1 concentration (mean: 188 pg/mL) compared to other tumor types." (PMID 40351765, 2025).